PMEPA1 (prostate transmembrane protein, androgen induced 1)
Diseases named in the same sentence as PMEPA1 in open-access papers (continued):
Sharing a sentence is not in itself a finding about the gene and the disease.
glioblastoma (2 papers, 2020 to 2025). The most malignant astrocytic tumor (WHO grade IV). "One potential pathway for protein degradation could involve exocytosis, similar to the release of extracellular vesicles loaded with PMEPA1 mRNA from glioblastoma stem cells." (PMID 40649997, 2025).
lymph node metastasis (2 papers, 2019 to 2021). "In TCGA, PMEPA1 correlated to poor prognosis in patients with lower T classification (Ta+T1+T2), lower M classification (M0), high grade (III), smoking, male patients, low immune infiltration levels of TME, and without lymph node metastasis (N0)." (PMID 34777336, 2021). "In Xiangya cohort, PMEPA1 correlated with poor prognosis for OS in patients with lower T classification (Ta+T1+T2), high grade (III), male patients, high macrophages infiltration level and without lymph node metastasis (N0)." (PMID 34777336, 2021).
renal cell carcinoma (2 papers, 2016 to 2020). "Further, another transcript described as solid tumor-associated 1 protein (STAG1)/transmembrane prostate androgen induced protein (TMEPA1) with 287 aa (PMEPA1-a) in renal cell carcinoma." (PMID 32064040, 2020).
adenoma (1 paper, 2012). A neoplasm arising from the epithelium. "C13orf27 and PMEPA1 with increased copy number in both adenoma and carcinoma were over expressed in rectal cancer tissues." (PMID 23158542, 2012). "Of them, copy number and mRNA expression of EFNA1 increased from rectal adenoma to carcinoma, and C13orf27 and PMEPA1 with gains in both adenoma and carcinoma were overexpressed in rectal cancer tissues." (PMID 23158542, 2012).
atherosclerosis (1 paper, 2021). A disease characterized by the build-up of fatty material and calcium deposition in the arterial wall resulting in partial or complete occlusion of the arterial lumen. "Overlap of the three protein coding genes (and protein names) with atherosclerosis in PubMed yielded 1 hit for Zbp1, 9 hits for Pck1, and 0 hits for Pmepa1." (PMID 35052410, 2021). "To date, Pmepa1 has not been studied in vascular biology or atherosclerosis." (PMID 35052410, 2021).
bladder tumor (1 paper, 2024). "Through analyzing the expression correlation of bladder tumor tissues based on the TCGA database, we also found a significant positive correlation between PMEPA1 and most autophagy related genes." (PMID 38385084, 2024). "Furthermore, interfering with PMEPA1 after knocking down METTL16 inhibited proliferation of bladder tumor cells, while increased the rate of cisplatin-induction apoptosis, the sensitivity of cells to cisplatin and the expression of apoptosis related protein." (PMID 38385084, 2024).
cervical cancer (1 paper, 2022). A primary or metastatic malignant neoplasm involving the cervix. "However, the clinical significance of PMEPA1 expression in cervical cancer (CC) and its contribution to cancer immunity have not been investigated." (PMID 35497877, 2022).
cholesteatoma (1 paper, 2023). A pathologic process characterized by the proliferation of keratinizing squamous epithelium resulting in the accumulation of keratin and cells in the middle ear and/or mastoid. "The expression of TMEM119 and PMEPA1 may reflect the characteristics of subcluster 8; these genes may promote the development and progression of bone destruction in cholesteatoma." (PMID 37537159, 2023).
colorectal adenocarcinoma (1 paper, 2021). The most common type of colorectal carcinoma. "PMEPA1 has been found to be highly expressed in normal colon and most colorectal adenocarcinomas and metastases, but it would be interesting to compare tumors that actively disperse CTCs with others that do not." (PMID 35153760, 2021).
Fuchs' endothelial dystrophy (1 paper, 2023). Fuchs endothelial corneal dystrophy (FECD) is the most frequent form of posterior corneal dystrophy and is characterized by excrescences on a thickened Descemet membrane (corneal guttae), generalized corneal edema, with gradually decreased visual acuity. "In the corneal endothelium, a PMEPA1 downregulation has been found in patients with Fuchs endothelial dystrophy, however, the exact molecular function is unclear." (PMID 36769200, 2023).
glioma (1 paper, 2020). A benign or malignant brain and spinal cord tumor that arises from glial cells (astrocytes, oligodendrocytes, ependymal cells). "Based on this prior knowledge, our aim was to unravel the underlying mechanisms of PMEPA1 function in human glioma progression." (PMID 31605013, 2020). "Within the Hippo pathway, we here demonstrate, in human gliomas, a functional interaction of a transmembrane protein, prostate transmembrane protein, androgen induced 1 (PMEPA1) with large tumor suppressor kinase 1 (LATS1)." (PMID 31605013, 2020). "We therefore evaluated expression levels of the PMEPA1 isoforms in our glioma cell lines, using PCR primers specific for PMEPA1a, PMEPA1b, PMEPA1c, and PMEPA1d transcripts." (PMID 31605013, 2020). "In our study, we performed both gain- and loss-of-function experiments in vitro and in vivo to demonstrate that PMEPA1 plays an oncogenic role in glioma progression." (PMID 31605013, 2020). "The PMEPA1 isoform PMEPA1a was predominantly expressed in glioma specimens and cell lines, and ectopic expression of the protein promoted glioma growth and invasion in vitro and in an orthotopic xenograft model in nude mice." (PMID 31605013, 2020). "In conclusion, our study demonstrates that membrane-bound PMEPA1, especially PMEPA1a, plays an oncogenic role in glioma progression." (PMID 31605013, 2020). "We show that PMEPA1 is upregulated in primary human gliomas." (PMID 31605013, 2020). "We found that PMEPA1 protein levels were increased in high grade gliomas (WHO III–IV; n = 40) relative to normal brain tissues (n = 6) and low grade gliomas (WHO II; n = 20)." (PMID 31605013, 2020). "PMEPA1 protein levels were also increased in glioma cell lines relative to NHA in culture, except in the case of U87MG, where PMEPA1 were nearly undetectable (NHA)." (PMID 31605013, 2020). "We also assessed expression levels of PMEPA1 isoforms in a cohort of primary glioma and nonneoplastic brain tissue samples." (PMID 31605013, 2020). "In this study, we show that the PMEPA1 protein is overexpressed in primary human glioma tissues and cell lines relative to nonneoplastic brain tissue samples and normal human astrocytes (NHA), where PMEPA1a is the predominant isoform in glioma samples and cell lines." (PMID 31605013, 2020). "However, how PMEPA1 isoform a had a significant oncogenic function in glioma is not clear." (PMID 31605013, 2020).
hepatocellular carcinoma (1 paper, 2025). A malignant tumor that arises from hepatocytes. "Direct oncogenic role of PMEPA1 in hepatocellular carcinoma has been recently shown on an animal model." (PMID 40649997, 2025).
liver cancer (1 paper, 2021). An epithelial or non-epithelial malignant neoplasm that arises from the liver. "The results support the hypothesis that PMEPA1 may be a major TGFβ effector and serve as a target for c-MYC activated liver cancer treatment." (PMID 33608500, 2021). "Moreover, we found that PMEPA1 mRNA expression is upregulated in human HCC samples, and its level correlates with TGFβ1, TGFβ2, and TGFβ3 mRNA expression in TCGA liver cancer samples." (PMID 33608500, 2021).
Pca (1 paper, 2022). "The regulator of TGF-β signal transduction, prostate transmembrane protein androgen-induced 1 (PMEPA1), has an inhibitory effect on Pca bone metastasis." (PMID 36147907, 2022).
rectal adenoma (1 paper, 2012). "Array CGH found that copy number increase of GPNMB (7p15.2), OXGR1 (13q32.1), C13orf27 (13q32.2-q34), PMEPA1 (20q13.31), PHACTR3 (20q13.32) and decrease of SMAD4 (18q21.2), BCL2 (18q21.33) occurred in both rectal adenoma and carcinoma." (PMID 23158542, 2012).
rectal cancer (1 paper, 2012). A primary or metastatic malignant neoplasm that affects the rectum. "Our real-time PCR results showed that C13orf27 and PMEPA1 were overexpressed in rectal cancer tissues comparing with paracancerous normal tissues." (PMID 23158542, 2012). "PMEPA1 is over-expressed in prostate, breast, renal cell, stomach and rectal carcinomas." (PMID 23158542, 2012). "In summary, we identified EFNA1 (1q), C13orf27 (13q), PMEPA1 (20q), GPNMB (7q) as candidate driving genes of genomic aberrations in rectal cancer." (PMID 23158542, 2012).
schistosomiasis (1 paper, 2022). An infectious disease caused by parasitic trematodes of the genus Schistosoma that colonize human blood vessels and release eggs that can cause granulomatous reactions leading to acute (swimmer's itch or acute schistosomiasis syndrome) or chronic disease. "Our analyses also indicated that ITIH4, PMEPA1, and MAMSTR are potentially causal genes affecting the severity of schistosomiasis." (PMID 35493725, 2022). "PMEPA1 is upregulated in the liver of mice with severe schistosomiasis." (PMID 35493725, 2022).
cancer (46 papers, 2012 to 2025). A tumor composed of atypical neoplastic, often pleomorphic cells that invade other tissues. "Finally, the pan-cancer assays revealed that PMEPA1 expression was associated with the overall survival of UVM, PAAD, LUSC, BLCA, CESC, and LUAD." (PMID 35497877, 2022). "We also provided an underlying mechanism by which PMEPA1 expression might modulate the malignancy of cancer cells and the inflammation and immune infiltration levels of TME." (PMID 34777336, 2021). "Finally, both CRP and FFV PEVs significantly upregulated gene expression of ECM components (e.g. MMP14, MMP16, collagen type V alpha 1 chain, versican) as well as the genes SERPINE1 and PMEPA1, which are associated with epithelial-to-mesenchymal transition in various cancer types." (PMID 39695652, 2024). "Cytoskeletal regulators (MYL9, TAGLN) and transcription factors (SNAI2) promote EMT and cancer stemness, while PMEPA1, IL6, IL8, IGFBP3, INHBA, and VEGFA contribute to proliferation, angiogenesis, and immune modulation." (PMID 41009714, 2025). "In the present study, we demonstrate that the mRNA expression levels of PMEPA1 are altered not only in cancer cells but also in mesenchymal stem cells during in vitro PC3 and MSC co-culture." (PMID 40649997, 2025). "Despite the observed elevation of TGF-β and PMEPA1 expressions at the mRNA level, protein analyses indicated a decrease in their levels in MSCs co-cultured with cancer cells for 72 h." (PMID 40649997, 2025). "Prostate transmembrane protein androgen induced 1 (PMEPA1) regulates cancer cell progression; it reportedly controls proton production by osteoclasts." (PMID 37537159, 2023). "Previous several studies have reported that PMEPA1 is vital for the regulation of cancer proliferation and metastases." (PMID 35497877, 2022). "To further explore the prognostic value of PMEPA1 in different types of tumors, we performed pan-cancer assays." (PMID 35497877, 2022). "The results from the difference and correlation analyses showed that seven types of cancer-infiltrating immunocytes were related to the expressions of PMEPA1." (PMID 35497877, 2022). "Although some previous researches have discovered the aberrant regulation of PMEPA1 in some cancers." (PMID 35497877, 2022). "Pmepa1 has been mostly studied in cancer, where it promotes proliferation, invasion, and migration via a PTEN-AKT pathway." (PMID 35052410, 2021). "Transmembrane prostate androgen-induced protein (TMEPAI), also known as PMEPA1, is highly expressed in many types of cancer and promotes oncogenic abilities." (PMID 34638419, 2021). "GO, KEGG, and GSEA analysis indicated that PMEPA1 was involved in cancer progression and the tumor microenvironment (TME)." (PMID 34777336, 2021). "Studies have also reported that altered PMEPA1 expression accelerates cancer cell growth and metastasis and therefore influences disease prognosis." (PMID 33639650, 2021). "As PMEPA1 has been shown to regulate EMT in the cancer progression, the action of linc00941/miR-877-3p/PMEPA1 axis in regulating EMT in KYSE-510 cells was further explored." (PMID 34254950, 2021). "A number of studies have shown that PMEPA1 induces degradation of several proteins critical to the development of cancer, such as androgen receptor, TGF-β type I receptor, Smad 2/3 proteins, and c-Maf." (PMID 31605013, 2020). "Future studies of PMEPA1 isoforms in prostate and other cancers will greatly benefit the utility of disease prognostic determination and therapeutic stratification." (PMID 32064040, 2020). "The dissection of biological function domains of PMEPA1 isoforms associated with AR and TGF-beta signaling potentially lead to novel anti-cancer therapeutics development." (PMID 32842649, 2020). "This review highlights the pleiotropic nature of PMEPA1 gene isoforms in the context of molecular structures and cancer biology, especially androgen and TGF-β signaling." (PMID 32842649, 2020).
cancer (continued). "Prostate transmembrane protein androgen induced 1 (PMEPA1) has been reported to promote cancer progression." (PMID 30887697, 2019). "Further, we have also provided supportive data to show that Smad3 dependent expression of TMEPAI/PMEPA1 contributes to the growth of cancer cells and invasion." (PMID 31798766, 2019). "In the present study, we validated six direct targets of EZH2 that are GPNMB, PMEPA1, CoL5A1, VGLL4, POMT2 and SUMF1 associated with cancer related pathways." (PMID 30760814, 2019). "The upregulated lnc-PMEPA1-2:1 is a 361 bp sense-overlapping lncRNA and was predicted to have a cis target gene, prostate transmembrane protein, androgen-induced 1(PMEPA1), which is important in cancer development." (PMID 28511643, 2017). "In this report, we present new findings on the cancer biologic properties of decreased PMEPA1 expression." (PMID 25883222, 2015). "While parental LNCaP cells exhibited severe growth inhibition in response to AR siRNA, simultaneous knockdown of PMEPA1 rescued the growth of cancer cells." (PMID 25883222, 2015). "Further research is essential to fully understand PMEPA1’s implications in cancer biology and how it might influence tumor microenvironment." (PMID 40649997, 2025). "However, we recognize that further investigation into PMEPA1 expression in normal cells, as well as its induced expression across various stromal cell populations influenced by cancer cells, is essential for the formulation of effective treatment strategies." (PMID 40649997, 2025). "We observed PMEPA1 with the highest difference in 5hmC status between cancer and normal tissue." (PMID 37628686, 2023). "Taken together, PMEPA1 is a prognosis-related biomarker for multiple cancer types, especially CC." (PMID 35497877, 2022). "Previous studies have already revealed the different roles of PMEPA1 in various cancers." (PMID 31605013, 2020). "Other reports suggested that PMEPA1 could promote cell proliferation in cancer cells and convert TGFβ/Activin signaling from a tumor suppressor to tumor promoting pathway." (PMID 31328883, 2019). "Moreover, we built stable PMEPA1 overexpressed and PMEPA1‐knockdown CRC cell lines to demonstrate that PMEPA1 promotes the cancer cell proliferation via inhibiting G1/S cell cycle arrest and inducing EMT related tumour metastasis." (PMID 30887697, 2019). "In some types of cancer, PMEPA1 has been reported to promote cancer metastasis." (PMID 30887697, 2019). "In addition, previous studies have reported the potential of function of PMEPA1 in some cancers." (PMID 35497877, 2022). "Finally, the prognostic value of PMEPA1 was validated in pan-cancer." (PMID 35497877, 2022). "According to pathway enrichment analysis, both PMEPA1 and TIMP1 primarily affect cytokine activity and the classic WNT signaling pathway, playing a crucial role in cancer development." (PMID 40244296, 2025). "As EMT is a critical process in cancer cell migration and distal metastasis and PMEPA1 is an important regulator for EMT, we further examined if linc00941/miR-877-3p/PMEPA1 axis regulates EMT in ESCC cells." (PMID 34254950, 2021). "Though the role of linc00941 has been reported in other cancers, we reported the role of linc00941 in ESCC and also demonstrated the importance of the novel linc00941/miR-877-3p/PMEPA1 axis in ESCC progression." (PMID 34254950, 2021). "Genes such FAM182A, SOX9, AHNAK2, ENSG00000121031, FLT3LG, PMEPA1, ZFP36L2 in the large intestine, ALB, KRTAP19-1, APOB, CD200, CRYGD, KRTAP24-1, OR6N2 in the liver are novel predictions, and their functions in these cancers can further be studied." (PMID 34997044, 2022). "Interestingly, some genes of the amplicon for which data are available in the human protein atlas, such as PCK1, PMEPA1, and RBM38, are expressed in the protein level at low to moderate levels in several cancers." (PMID 30275357, 2018).
cancer (continued). "The products of several genes from our potential cell surface list are suspected of playing key roles in more general cancer-related activities such as immunosuppression/evasion (CD14 and CD86), cell migration (ICAM, CDH11) and proliferation (TGFB1, PMEPA1, PDGFRL, SLC19A3)." (PMID 27363029, 2016). "The results showed that several canonical pathways that are involved in cancer invasion and TME, such as “extracellular structure organization”, “cell-substrate adhesion”, “cell-matrix adhesion”, and “cell-substrate junction assembly” were particularly enriched in the high-PMEPA1 group." (PMID 34777336, 2021). "Only two of the 44 significant genes (PMEPA1 and CCL19) from our cancer/neoplasia/normal classification analysis are not significant in the TCGA dataset (adjusted P-values >0.05)." (PMID 24887547, 2014).